STK40 (serine/threonine kinase 40)
Synonyms: SgK495; SHIK; MGC4796
Tractability: Small molecule: it belongs to a druggable protein family. PROTAC: it is named in the literature on targeted protein degradation; ubiquitination databases record sites on it.
Gene: Protein-coding gene on chromosome 1 (36,339,620 to 36,385,927, reverse strand). Ensembl gene ENSG00000196182.
Subcellular location: Nucleus; Cytoplasm
Subcellular location (Human Protein Atlas): Cytosol; Nucleoplasm
Gene Ontology:
Molecular function: protein binding; ATP binding; protein kinase activity; protein serine kinase activity; protein serine/threonine kinase activity
Biological process: regulation of MAPK cascade
Cellular component: cytosol; nucleoplasm; cytoplasm; nucleus
Genetic constraint (gnomAD): Loss-of-function variants: 13 observed, 49.69 expected, observed/expected ratio (o/e) 0.26, 90% interval 0.17 to 0.42. The upper end of that interval is the gene's LOEUF score, 0.42, which puts it in group 1 of 6, group 1 being the genes least tolerant of losing a copy. Missense variants: 460 observed, 610.42 expected, observed/expected ratio (o/e) 0.75, 90% interval 0.7 to 0.81. Synonymous variants: 225 observed, 247.74 expected, observed/expected ratio (o/e) 0.91, 90% interval 0.81 to 1.01.
Homologues: Orthologues: chimpanzee STK40 (100% identical), macaque STK40 (99% identical), rabbit STK40 (99% identical), pig STK40 (98% identical), dog STK40 (98% identical), guinea pig STK40 (98% identical), mouse Stk40 (97% identical), rat Stk40 (97% identical), zebrafish stk40 (85% identical), tropical clawed frog stk40 (82% identical), Drosophila melanogaster trbl (19% identical). Paralogues in human: TRIB3 (24% identical), TRIB1 (23% identical), TRIB2 (20% identical).
Diseases named in the same sentence as STK40 in open-access papers:
STK40 is named in the same sentence as 23 diseases in open-access papers, as found by Europe PMC text mining. Sharing a sentence is not in itself a finding about the gene and the disease. The quoted sentences say what the papers report.
psoriasis (6 papers, 2015 to 2023). An autoimmune condition characterized by red, well-delineated plaques with silvery scales that are usually on the extensor surfaces and scalp. "It has been reported that activated NF-κB in psoriasis can induce miR-31 which subsequently can suppress STK40 to aid in further activation of NF-κB creating a positive feedback loop between miR-31 and NF-κB." (PMID 37010718, 2023). "The upregulation of miR-130a enhances keratinocyte proliferation by targeting serine/threonine kinase 40 (STK40) in psoriasis." (PMID 32806619, 2020). "In psoriasis, miR-31 targets serine/threonine kinase 40 (STK40), a negative regulator of NFkB, which in turn results in increased expression of proinflammatory cytokines and chemokines." (PMID 26318001, 2015). "Inflammatory cytokines can promote miRNA-31 transcription, and miRNA-31 participates in psoriasis inflammation through affecting the secretion of inflammatory cytokines by targeting serine/threonine kinase 40 (STK40) which can negatively regulate NF-kB pathway." (PMID 29088812, 2017).
breast carcinoma (4 papers, 2013 to 2025). "Overall, these results indicate that the little-studied protein kinase STK40 is crucial for breast cancer cell survival." (PMID 29854300, 2018). "Overall, these analyses indicate that STK40 is highly expressed in various cancers, including breast cancers, with stronger expression in TNBCs than in other breast cancer subtypes." (PMID 29854300, 2018). "We found that STK40 was more strongly expressed in TNBC than in other breast cancers, and that this molecule was overexpressed in various other types of cancer." (PMID 29854300, 2018). "Overall, our results identify STK40, a little-characterized protein, as a potential new treatment target in breast cancer." (PMID 29854300, 2018). "STK40 was found to be overexpressed in TNBCs, relative to other breast cancer subtypes, and in various other tumor types." (PMID 29854300, 2018). "We therefore looked at STK40 expression data for the publicly available TCGA cohort, which showed that STK40 was more strongly expressed in a subset of TNBCs than in other breast cancer subtypes." (PMID 29854300, 2018). "STK40 alterations were also identified in breast cancers (metastatic breast cancer project, TCGA cohort)." (PMID 29854300, 2018). "We then investigated STK40 expression in the different breast cancer subtypes." (PMID 29854300, 2018). "These known targets included CEBPα, STK40, and E2F2 which had been shown to be downregulated at mRNA level by miR-31-H in ovarian cancer cells and Frizzled3 (Fzd3) and MMP16 which were repressed at the protein level by miR-31 in MDA-MB-231 breast cancer cells." (PMID 23472152, 2013).
triple-negative breast carcinoma (3 papers, 2018 to 2025). An invasive breast carcinoma which is negative for expression of estrogen receptor (ER), progesterone receptor (PR), and human epidermal growth factor receptor 2 (HER2). "The gene with the eighth highest MS was STK40, whose depletion decreases cell viability and colony formation in triple-negative breast cancers (TNBCs)." (PMID 37761960, 2023).
anemia (2 papers, 2017 to 2019). A reduction in the number of red blood cells, the amount of hemoglobin, and/or the volume of packed red blood cells. "Together, these results reveal that loss of Stk40 can lead to fetal anemia, suggesting a role of Stk40 in regulating erythropoiesis." (PMID 28358362, 2017). "To test whether anemia in Stk40 mutants was caused by an inadequate supply of Epo, an essential cytokine for erythrocyte production, we examined the concentration of Epo in the plasma of E18.5 embryos by ELISA." (PMID 28358362, 2017). "Here we report that targeted deletion of Stk40 leads to fetal liver hypoplasia and anemia in the mouse embryo." (PMID 28358362, 2017). "The finding implied that anemia observed in Stk40−/− embryos was not caused by a low concentration of Epo." (PMID 28358362, 2017). "The presence of anemia in Stk40−/− embryos suggested that Stk40 deletion could result in hematopoietic defects." (PMID 28358362, 2017).
bladder cancer (2 papers, 2025). "Studies show that STK40 may be linked to unfavorable prognosis in gastric and bladder cancers due to its role as a cellular senescence gene." (PMID 40455337, 2025).
colon cancer (2 papers, 2017 to 2022). "In colon cancer, esophageal neoplasia, and lung cancer, miR-31 acts as an oncogenic miRNA by inhibiting the expression of E2F2, STK40, and PPP2R2A, respectively." (PMID 28783765, 2017). "The isoform miR-31-P targets and represses DICER by translational repression, whereas miR-31-M targets and represses CSBPα, STK40 and E2F2, in HCT116 colon cancer cells, suggesting that specific genes regulated by miR-31 might be isoform dependent." (PMID 34716428, 2022).
esophageal cancer (2 papers, 2018 to 2023). A primary or metastatic malignant neoplasm involving the esophagus. "High expression of STK40 has been closely correlated with the occurrence and development of esophageal cancer." (PMID 37915566, 2023). "More notably, miR-31 directly regulates Stk40 and activates the STK40-NF-κΒ-controlled inflammatory pathway in esophageal cancer." (PMID 30046565, 2018).
Obesity (2 papers, 2021 to 2024). Accumulation of substantial excess body fat. "For SAT, the amount of DE mRNAs of obesity was 185 (50 for overweight, 54 for obesity, and 107 for obesity with MS), and only 3 mRNAs (JSRP1, MRS2 and STK40) were shared by all these 3 obesity components as shown in Venn diagram." (PMID 34621242, 2021).
gastric cancer (1 paper, 2023). A primary or metastatic malignant neoplasm involving the stomach. "Last but not least, we identified STK40 as a key senescence-related gene in gastric cancer, and determined that STK40 can affect ROS accumulation and cell proliferation in gastric cancer cells." (PMID 37915566, 2023). "In vitro experiments showed that ROS accumulation and cell proliferation ability of gastric cancer cells were impaired when STK40 was knocked down." (PMID 37915566, 2023). "When we knocked down STK40 expression in gastric cancer cells using siSTK40-1 and siSTK40-2, the proliferation ability of gastric cancer cells was significantly impaired." (PMID 37915566, 2023). "First, we explored the expression of STK40 in 10 pairs of gastric cancer tissues, and the results showed that the expression of STK40 in gastric cancer tissues was significantly higher than that in adjacent normal tissues." (PMID 37915566, 2023). "This provides a partial reference for the mechanism by which STK40 affects the proliferation ability of gastric cancer cells." (PMID 37915566, 2023). "The results showed that the proliferation ability of gastric cancer cell lines was significantly weakened after the expression of STK40 was reduced." (PMID 37915566, 2023). "It is worth noting that STK40, as a key gene in model construction, still lacks relevant research in gastric cancer." (PMID 37915566, 2023). "The results showed that the accumulation of ROS in gastric cancer cells was significantly impaired after the expression of STK40 was reduced." (PMID 37915566, 2023). "Therefore, we believe that STK40 is one of the most critical senescence-related genes in gastric cancer, which needs further study." (PMID 37915566, 2023). "Then, we deeply explored the biological function of STK40 in gastric cancer." (PMID 37915566, 2023). "Finally, we also believe that STK40 is the most critical senescence-related gene affecting the progression of gastric cancer." (PMID 37915566, 2023). "Therefore, we further explored whether STK40 acts as one of the factors affecting gastric cancer progression." (PMID 37915566, 2023). "Therefore, we further explored whether STK40 affects intracellular ROS content, and the results showed that reduced expression of STK40 could significantly reduce ROS accumulation in gastric cancer cells." (PMID 37915566, 2023).
melanoma (1 paper, 2024). A malignant, usually aggressive tumor composed of atypical, neoplastic melanocytes. "Regarding exclusively mutated genes in dormant melanoma B16-F1GFP-D cells, we observed 34 mutations that may lead to AA changes, while two nonsense mutations were observed in the Cars (W416*) and Stk40 (Q386*) genes." (PMID 39223638, 2024).
respiratory failure (1 paper, 2018). The significant impairment of gas exchange within the lungs resulting in hypoxia, hypercarbia, or both, to the extent that organ tissue perfusion is severely compromised. "STK40 knockout mice display respiratory failure, possibly due to inadequate epithelial cell differentiation." (PMID 29854300, 2018).
retinoblastoma (1 paper, 2015). A malignant tumor that originates in the nuclear layer of the retina. "We did not detect significant changes in cell proliferation following reduction of PPP6C or STK40 in either retinoblastoma cell line." (PMID 26379276, 2015). "To improve our understanding of miRNA-31 and/or -200a mediated regulation in retinoblastoma cells, we also evaluated the extent of repression of STK40, PPP6C, and DLL3 in Weri1 cells to determine if these miRNA-mRNA interactions remained intact." (PMID 26379276, 2015). "Furthermore, our work is the first to demonstrate that overexpression of miRNA-31 and/or miR-200a results in differential gene expression patterns of ACOT7, DLL3, PPP6C, and STK40 between two phenotypically different retinoblastoma cell lines." (PMID 26379276, 2015).
uterine carcinoma (1 paper, 2018). A carcinoma involving a uterus. "Moreover, STK40 is overexpressed in various cancers, including ovarian and uterine carcinomas." (PMID 29854300, 2018).
tumor (11 papers, 2014 to 2025). "A recent evidence displayed that STK40 acted as a tumor inhibitor in patients with Triple-negative breast cancers." (PMID 36505846, 2022). "Depletions of LRP5, LRP6 or STK40 delayed tumor growth to similar extents in a statistically different manner." (PMID 29854300, 2018). "We found that the depletion of LRP5, LRP6 or STK40 slowed tumor growth in an MDA-MB-468-derived xenograft model." (PMID 29854300, 2018). "E2F2 is a tumor suppressor that inhibits the cell cycle, while STK40 acts as a negative regulator of NF-kB-mediated transcription." (PMID 28783765, 2017). "To explore the esophagus-specific functional relationships for Fbxw7, Stk40, and Pdcd4 (tumor-suppressor targets of miR-223, -31, -21), we employed FNTM for the rat." (PMID 26918602, 2016). "The mRNA levels of Fbxw7 and Stk40 in all 3 ZD tumor groups were statistically significantly reduced as compared to ZST esophagus (**P < 0.01, ***P < 0.001)." (PMID 26918602, 2016). "To explore molecular mechanisms underlying miR-31-mediated tumor-suppression, we examined the expression of E2F2 and STK40, two known downstream target oncogenes for miR-31." (PMID 25568668, 2014). "Real-time RT-PCR also showed that miR-31 was able to downregulate the expression of E2F2 and STK40 after p21 shRNA treatment, further demonstrating that the tumor-suppressive effects of miR-31 were dependent on reduced p21 expression." (PMID 25568668, 2014). "STK40 exhibited a disparity, as it increased in primary tumours (53.08%), such as RAN (49.66%)." (PMID 39223638, 2024). "The knockdown of STK40 also delays tumor growth in in vivo experiments." (PMID 37761960, 2023). "In addition, STK40 knockdown impaired growth in an anchorage-independent manner in vitro and slowed tumor growth in vivo." (PMID 29854300, 2018). "Thus, upregulation of oncogenic miR-223, -31, and -21 is accompanied by down-regulation of their respective tumor suppressor target Fbxw7, Stk40 and Pdcd4." (PMID 26918602, 2016). "Additionally, Fbxw7, Pdcd4, and Stk40 (tumor-suppressor targets of miR-223, -21, and -31) were downregulated in marked-ZD cohort." (PMID 26918602, 2016). "Specifically, the CXCL1, IFNG, and SERPINE1 in the tumor group had higher expression, while PIM1 and STK40 in the tumor group had lower expression." (PMID 40455337, 2025). "Our findings suggest that the tumor-promoting effects of STK32C and STK40 in TNBC may be achieved through the regulation of YAP/TAZ." (PMID 40869130, 2025). "Interestingly, genes with oncogenic potential, including CDC42, CDC14B, STK40, BRD3, CPNE1, and MCM3, were downregulated, whereas tumor inhibitors, including CDKN2C, CASP7, and CDKN1B, were upregulated by RBM15 depletion." (PMID 38825643, 2024). "Immunohistochemical analysis showed that FBXW7, STK40, and PDCD4 protein was moderately/strongly expressed in the basal/suprabasal cells of ZST esophagus, but reduced or absent in hyperplastic/tumor-bearing ZD3T, ZD6T, and ZD12T esophagus." (PMID 26918602, 2016). "STK40 has not yet been studied in the field of cancer, but our findings indicate that it is overexpressed, not only in TNBC, but also in other types of cancer, implying a possible role in tumor induction and/or progression." (PMID 29854300, 2018).
cancer (8 papers, 2016 to 2025). A tumor composed of atypical neoplastic, often pleomorphic cells that invade other tissues. "The expression details and functions of STK40 in various cancer types still warrants further investigation." (PMID 36505846, 2022). "ROS often play a double-edged sword role in cancer, and whether and how STK40 affects ROS accumulation was previously unknown." (PMID 37915566, 2023). "Belonging to the Tribbles pseudokinases family, STK40 is seen as a marker of cancer progression." (PMID 37752559, 2023). "Although we focused on RBM15 and serine metabolism in this study, network analysis revealed that the relationship between RBM15 and other genes with oncogenic potential (CDC42, CDC14B, STK40, BRD3, CPNE1, and MCM3) is also crucial for cancer cell survival." (PMID 38825643, 2024).
STK40 also shares sentences with these, for which no sentence is quoted: Alzheimer disease (1 paper); bacterial infection (1); cardiovascular disease (1); diabetes mellitus (1); leukemia (1); lung carcinoma (1); ovarian carcinoma (1); thalassemia (1).